CCND1 (cyclin D1)
Diseases named in the same sentence as CCND1 in open-access papers (continued):
Sharing a sentence is not in itself a finding about the gene and the disease.
breast cancer (continued). "Nevertheless mRNA levels might provide a more accurate prediction of prognosis in breast cancer patients concerning CCND1 amplification and this should be further examined." (PMID 39586971, 2025). "In breast cancer, NF-κB-driven overexpression of Bcl-2 enhances chemoresistance and metastatic potential, whereas pharmacological suppression of NF-κB (e.g., via chrysophanol) downregulates Bcl-2 and cyclin D1, restoring apoptotic sensitivity." (PMID 40562870, 2025). "The expression of CCND1 is increased in almost all types of human cancers, including breast cancer." (PMID 41263459, 2025). "ETS-1 directly activates cyclin D1 transcription by binding to its promoter, resulting in increased Cyclin D1 protein levels, which accelerate the progression through the G1/S checkpoint and increase breast cancer cell proliferation." (PMID 40181983, 2025). "The molecular mechanisms underpinning CCND1 dysregulation in these cancers appear to be similar to those observed in breast cancer, suggesting that circFOXK2 may serve as a central modulator of CCND1 expression across various malignancies." (PMID 40233410, 2025). "Like cyclin D1, c-MYC is an oncogene that regulates cell growth and cell proliferation at the G1 transition, and its amplification is associated with aggressive tumor behavior and poor outcome in patients with breast cancer." (PMID 39804138, 2025). "Also, hyperglycemia was reported to increase the proliferation of breast cancer cells by upregulating cdk2 (cyclin dependent kinase 2) and cyclin D1, which in-turn accelerate the cell cycle progression." (PMID 40735043, 2025). "Furthermore, the IGF‐1 receptor (IGF‐1R) can activate the Ras/Raf/MEK/ERK signaling pathway, enhancing the expression of cyclin D1 and accelerating the G1/S phase transition, thus promoting the proliferative capacity of breast cancer cells." (PMID 40550558, 2025). "In vitro drug sensitivity studies suggest deregulated Cyclin D1 may contribute to HNSCC chemoresistance, and CDK4/6 inhibitors that inhibit Cyclin D1 activity have shown substantial clinical improvement in breast cancer." (PMID 41465166, 2025). "Additionally, the expression of Cyclin D1, a protein typically overexpressed in breast cancer cells, was significantly decreased following clozapine treatment, particularly after 18 hours of exposure." (PMID 40531900, 2025). "CCND1 expression is closely related to the tumorigenesis and progression of breast cancer." (PMID 41263459, 2025). "Overall, we demonstrate how ErbB2 receptor levels modulate the roles of cyclin D1 and c-Myc in the G1/S transition and suggest that variations in ErbB2 levels within breast cancer tissues confer heterogeneous sensitivity to CDK4 inhibitors, potentially complicating treatment." (PMID 41161384, 2025). "Specifically, METTL3 association with the CCND1 (cyclin D1) promoter region was reduced with STAT5B knockdown, but not STAT5A, which impaired cell cycle progression in hormone receptor-positive MCF7 breast cancer cells." (PMID 40507264, 2025). "Cyclin-D1 overexpression has been reported in many breast cancers, and cyclin-D1 may be a promising target for breast cancer treatment." (PMID 38172758, 2024). "In murine models, cyclin D1 was required for the growth of ErbB2-induced mammary tumors." (PMID 38191593, 2024). "Our findings suggest that cyclin D1 overexpression may adapt cells to increased compressive stress, possibly contributing to its prevalence in cancers such as breast cancer by allowing continued proliferation in mechanically challenging environments." (PMID 38478555, 2024). "The inhibition of ZKSCAN3 using shRNA in MCF-7 and MDA-MB-231 cells diminishes cell viability, migration, and invasion, highlighting that ZKSCAN3-shRNA significantly decreases the expression of MMP-2, MMP-9, CCND1, and Bcl-2 while augmenting the expression of Bax in breast cancer cells." (PMID 39519085, 2024).
breast cancer (continued). "In addition, it has been reported that Cyclin D1 amplification is widely observed (29 to 58%) in ER+ breast cancer." (PMID 38957324, 2024). "This leads to an increased level of Cyclin D1 protein in breast cancer cells." (PMID 39439957, 2024). "However, the introduction of a MyD88 inhibitor disrupted the signal transduction of the TLR3-MyD88-NF-κB (p65)-IL6-Cyclin D1 pathway, leading to reduced breast cancer cell proliferation." (PMID 38347830, 2024). "Furthermore, scatter plot of cyclin D1 and Top2A abundance by breast cancer subtype depicts the significant correlation between cyclin D1 and Top2A in luminal B (r = 0.08." (PMID 38191593, 2024). "It is possible that enhancer hijacking may serve as an additional mechanism for CCND1 overexpression in breast cancer." (PMID 39033128, 2024). "RORA gene expression has been associated with decreased proliferation and invasion because it inhibits the Wnt/β-catenin pathway, preventing the transformation and progression of some types of cancer, such as breast cancer and negatively regulates genes such as c-jun, c-myc and cyclin D1." (PMID 39010137, 2024). "Additionally, Shp2 has been found to enhance the proliferation of breast cancer cells by regulating Cyclin D1 stability through the PI3K/Akt and GSK3β pathway." (PMID 39117618, 2024). "By contrast, the increased interactions within cytoband 11q13.1 in Luminal A and B subtypes are indicative of dysregulation in regions harboring CCND1, a well-known regulator of the cell cycle, which is often amplified in breast cancer and drives abnormal cell proliferation." (PMID 39596229, 2024). "Notably, the clinical approval of inhibitors targeting CDK4/6, whose activity is determined by cyclin D1 protein level, highlights the pronounced clinical significance of cyclin D1 in the context of cancer therapeutics, particularly for breast cancer." (PMID 38551001, 2024). "In breast cancer patients, amplification of the CCND1 gene may occur in up to 15% of patients, and overexpression of cyclin D1 protein is even more common, occurring in 50% of tumors." (PMID 38831405, 2024). "Cyclin D1 is a cell cycle regulator that is overexpressed in breast cancer." (PMID 39328201, 2024). "Other in vitro analyses suggest that statin antiproliferative action may be due to an effect on cyclin D1 (oncogene) and p27 (tumor suppressor) through up-regulated expression of p27 and down-regulated expression of cyclin D1 in breast cancer cells." (PMID 39273534, 2024). "Furthermore, a recent investigation on breast cancer demonstrated that miR-34c targets CCND1, CDK4, and CDK6, pivotal cell cycle regulators that prompt arrest at the G2/M stage." (PMID 39097731, 2024). "Furthermore, reports showed that kaempferol elicited in vitro and in vivo anticancer activity against breast cancer by down-regulating the expression of cyclin D1, cyclin E, cathepsin D, pIRS-1, pAkt, and pMEK1/2, while up-regulating p21 and Bax expression." (PMID 39478959, 2024). "CBD was also found to facilitate a PPAR-mediated apoptotic pathway in MDA-MB-231 cells and ER+ T-47D cells; the study by Sultan and co-workers demonstrated the upregulation of the transcription factor PPARy in breast cancer cell lines accompanied by the downregulation of mTOR and cyclin D1." (PMID 38891847, 2024). "Limited data exist regarding the role of CDK4/6 and cyclin D1 interaction in the development of palbociclib resistance, and effective targets for palbociclib-resistant ER+ and ER− breast cancers are largely unknown." (PMID 38473336, 2024). "Patients in stages 3 and 4 of breast cancer subtypes such as Her2, Luminal A, and Luminal B who test positive for CCND1, CTSD, EGFR, BCL2, and ESR1 gene expression might benefit in this regard." (PMID 39202273, 2024). "Cyclin D1 gene expression was found in breast cancer patients with a positive ER status." (PMID 39202273, 2024). "The cyclin D1 gene (CCND1) is amplified in approximately 20% of breast carcinomas." (PMID 38473336, 2024).
breast cancer (continued). "Nevertheless, the prognostic value of CCND1 overexpression is still controversial in breast cancer." (PMID 37024471, 2023). "Notably, the amplification of CCND1 is related to the poor prognosis of ER-positive breast cancer and ER-positive tamoxifen-treated breast cancer." (PMID 37024471, 2023). "Since the amplification of chromosome 11q13 was correlated with lymph node metastasis and increased mortality in patients with breast cancer, they studied the role of two genes located within this amplicon, CCND1 and CTTN, in the development of breast tumors using transgenic mice." (PMID 37761244, 2023). "While CDK6/cyclin D3 is linked to the hematopoietic system and is crucial for healthy thymus development and the maturation of bone marrow hematopoietic stem cells, CDK4/cyclin D1 is related to cell proliferation and is essential for supporting the progression of breast cancer." (PMID 37759823, 2023). "In breast cancer, the cyclin D1 overexpression may be attributed to an increase in CCND1 copy numbers." (PMID 37427143, 2023). "Therefore, this study aimed to explore the molecular mechanism of alternative splicing of CCND1 in breast cancer (BC) chemoresistance." (PMID 36915230, 2023). "In addition, salinomycin has been found to inhibit the expression of Cyclin D1 in prostate and breast cancers." (PMID 37914721, 2023). "Cyclin D1, frequently over-expressed in ESR1-mutated breast cancer, could activate the CDK4 and CDK6 to facilitate cell cycle progression through the G1 restriction point." (PMID 36624500, 2023). "In other words, the amplification or overexpression of Cyclin D1 and ERa in breast cancer may occur through the same pathway." (PMID 37828916, 2023). "Surprisingly, our data found that endocrine resistance pathways, which could be divided into 3 functional categories, ERBB2, BCL2, and CCND1, were upregulated in FA-derived breast cancer compared to FA component." (PMID 37328469, 2023). "Additionally, CCND1 amplification predicts reduced recurrence-free survival and overall survival in breast cancer patients treated with endocrine therapy." (PMID 38004441, 2023). "Additionally, the overexpression of Cyclin D1 in breast cancer cells showed higher sensitivity to palbociclib." (PMID 36900131, 2023). "Aberrant expression of CCND1 has been found in a variety of human cancers, including breast cancer." (PMID 37190123, 2023). "Furthermore, it acts as a breast cancer tumor suppressor, as it directly represses the expression of Ccnd1 and Foxf1, a potent inducer of epithelial-mesenchymal transition (EMT), invasiveness, and tumorigenicity." (PMID 37353485, 2023). "A down-regulation of the expression of cyclin D1 in stiffness-dependent manner was detected, demonstrating that the expression of cyclin D1 could be a marker of sensitiveness of these breast cancer cells to this physical factor." (PMID 38046276, 2023). "The uncontrolled formation of cyclin D1 and CDK 4/6 complexes plays an integral role in both the initiation and progression of breast cancer and may be associated with endocrine resistance." (PMID 37667421, 2023). "It was reported that approximately 15–20% of breast cancer contained the amplification of CCND1." (PMID 37024471, 2023). "In addition, in breast cancer tumor tissues of ERa (+) breast cancer patients, Cyclin D1 overexpression was also observed in samples with Cav-1 mutations." (PMID 37828916, 2023). "Most studies showed that CCND1 overexpression could be considered as a marker of good prognosis in breast cancer." (PMID 37024471, 2023). "Furthermore, a similar pattern of AR/BAD binding to the ARE site from the cyclin D1 promoter was observed in T47D breast cancer cells." (PMID 37686282, 2023).
breast cancer (continued). "Cyclin D1 overexpression increases stem cell-like behaviors and migrations in estrogen receptor (ER)-positive breast cancer, while the opposite is seen in ER-negative cells, thus reflecting the fundamentally different effects of cyclin D1 expression in ER-positive and ER-negative breast cancers." (PMID 36675501, 2023). "The role of ROS in breast cancer is based on intracellular levels; at low levels, ROS can promote proliferation in cancer by stimulating cyclin D1 expression, triggering ERK phosphorylation and MAPK activation, which are all associated with carcinogenesis and cancer cell survival." (PMID 37400769, 2023). "While the overexpression of CCND1 was observed in more than 50% of breast cancer." (PMID 37024471, 2023). "CCND1 and EH37E0225350 endogenous expression was shown to be dependent on estrogen signaling, indicating that the active EH37E0225350 enhancer may be necessary for the activation of CCND1 expression by estrogen in breast cancer cells." (PMID 37012250, 2023). "However, some studies suggested that CCND1 overexpression was a poor prognostic marker in breast cancer." (PMID 37024471, 2023). "This miR-96 overexpression in breast cancer cells resulted in the modulation of the transition of G1/S cells due to the decreased expression of CDKs (cyclin-dependent kinases) p27 Kip1 and p21 and the increased expression of Cyclin D1." (PMID 36681070, 2023). "Cyclin D1 is induced early in breast cancer and CIN is an early feature of tumorigenesis that may precede tumor suppressor loss." (PMID 36358806, 2022). "To test this hypothesis, we knocked out CDKN1B in CCND1 amplified (MDA-MB-415) and CCND1 neutral (T47D) breast cancer cell lines." (PMID 35523804, 2022). "We also found a high expression of CCND1 in human breast cancer tissues compared to normal." (PMID 35622738, 2022). "In human breast cancer, p16INK4a is inversely correlated with cyclin D1 and ERα expression." (PMID 36358806, 2022). "Editing breast cancer tissue with anti-estrogen therapies provides the possibility to enhance pro-apoptotic processes by blocking the frequently occurring up-regulation of cyclin D1 in breast cancer cells with CDK4/6 inhibitors." (PMID 35814409, 2022). "Consequently, inactivation of SREBP1 in human liver and breast cancer cell lines reduces the expression of cyclin D1 and attenuates Rb phosphorylation." (PMID 36091143, 2022). "In addition, melatonin can inhibit the RNA expression level of cyclin D1 in human breast cancer cells and the RNA and protein expression levels of cyclin D1, cyclin B1, CDK1, and CDK4 in osteosarcoma cells." (PMID 36235740, 2022). "Cyclin D1 protein abundance is increased as a consequence of overexpression, gene amplification, transcriptional induction or post-transcriptional induction, in >50% of breast cancers." (PMID 36358806, 2022). "For example, Cyclin D1 oncogene was downregulated in breast cancer, increasing cell migration." (PMID 35216190, 2022). "PTEN, BRCA1, BRCA2, PI3K, and CCND1 genes were involved with the breast cancer signaling pathway." (PMID 36341349, 2022). "ERα enhances the growth rate of breast cancer cells via interaction with cyclin D1." (PMID 35764927, 2022). "Specifically, Nek5 was shown to enhance breast cancer cell mesenchymal morphology and migration, and was also shown to enhance breast cancer cell proliferation via upregulation of Cyclin A2 expression, while downregulating Cyclin D1, D3, and E1 expression." (PMID 35409400, 2022). "Another study reported miRNA-mediated epigenetic regulation of CCND1 in breast cancer cells." (PMID 35622738, 2022). "Estrogen promotes cyclin D1 expression in breast cancer cells." (PMID 35407638, 2022). "We show that the deficiency of the globin increased levels of both cyclin D1, a marker of poor prognosis in breast cancer patients, and cyclin E, without increasing cellular proliferation." (PMID 36232784, 2022).
breast cancer (continued). "Although cyclin D1 knockout mice were shown to be resistant to the formation of Erbb2 or Ras oncogene-induced breast cancers, cyclin D1 deficiency has not been shown to be protective against tumor formation induced by c-Myc or Wnt-1." (PMID 36017236, 2022). "Cyclin D1 is a key regulator of the cell cycle, mediating transition from the G1 to the S phase and has been recommended as a prognostic predictive marker for breast cancer cell proliferation and metastasis." (PMID 36143405, 2022). "The antiproliferative effect of arctiin on several types of human cancer cells, including osteosarcoma, colorectal cancer, melanoma, lung cancer, breast cancer, prostate cancer, and transformed renal cells, was reported to involve the downregulation of cyclin D1 expression." (PMID 35214097, 2022). "The researchers reported that D-limonene reduced the expression of cyclin D1, which may lead to cell-cycle arrest and reduced breast cancer cell proliferation." (PMID 35267408, 2022). "The inactivation of p16INK4a, a CDK inhibitor that inactivates CDK4/6 and prevents cell cycle progression at the G1/S checkpoint, resulting in the loss of cell cycle control, while dysregulation of the CDK4/6-cyclin D1 complex is a crucial stage in the genesis of breast cancer." (PMID 36406002, 2022). "Although it has been reported that CYCLIN D2 expression compensates for loss of CYCLIN D1 expression in Wnt-driven mammary tumors, neither CDK2 nor CDK6 appear to compensate for the absence of CDK4 expression." (PMID 36051751, 2022). "Cyclin D1 and G9a have been shown to be overexpressed in ERα+ breast cancer, suggesting that cyclin D1 and G9a may have synergistic roles." (PMID 35740522, 2022). "Previously it has been clearly shown that CCND1 was amplified in breast cancer." (PMID 36476410, 2022). "Prior study reported that RSK2 located in nucleus could enhance breast cancer cell proliferation through upregulation of cyclin D1 mRNA and protein level." (PMID 36210843, 2022). "Therefore, the interaction between ERα and cyclin D1 has been considered the most important mechanism of ERα to enhance the growth rate of breast cancer cells." (PMID 35764927, 2022). "While an increase of KDM3A is concomitant with a reduced H3K9me2/3 during breast tumorigenesis, KDM3A facilitated the activation of genes implicated in breast cancer as MYC, PAX3, Cyclin D1, MMP-9, S100A4, and JUN, thereby enhancing the proliferation and motility of breast cancer cells." (PMID 36185256, 2022). "Moreover, the data also showed that CCND1 gene amplification alone is a strong predictor of anti-hormonal therapy response in young-age breast cancer patients." (PMID 33920506, 2021). "It is conceivable that acetylation-dependent repression of Cyclin D1 expression might further contribute to the anti-proliferation activity of ELF5 in breast cancer." (PMID 33742100, 2021). "Notably, there is evidence that autophagy induction by IR and/or drug manipulation can induce CCND1 degradation not only in breast cancer, but also in hepatocellular carcinoma (HCC) and GB cells." (PMID 34445095, 2021). "In addition to cyclin D1, high-resolution live-cell imaging of breast cancer cells displayed ubiquitination of cyclin A2 in foci, further targeted by autophagy/lysosomal degradation." (PMID 35008317, 2021). "Authors based on bioinformatic tools, pathway enrichment and network analyses confirmed that Cyclin D1 overexpression, known for its oncogenic roles as regulator of cell cycle and breast cancer aggressiveness, could be a target of EGCG." (PMID 34444715, 2021). "Moreover, PHD1 regulation of cyclin D1 has further been demonstrated in breast cancer cells, whereupon inactivation of the Egln2 (Phd1) gene, cyclin D1 levels, and mammary gland cell proliferation decreased." (PMID 34062959, 2021).